IL2 (interleukin 2)
Diseases named in the same sentence as IL2 in open-access papers (continued):
Sharing a sentence is not in itself a finding about the gene and the disease.
tumor (continued). "Together, these results suggest that the combination therapy of Roxadustat and anti-PD-1 antibody promotes the induction of effector-like CD8+ T cells within the tumor, a process supported by Roxadustat-induced increased IL-2 production." (PMID 40343532, 2025). "Tumour acidosis (pH 6.2–6.5) impairs cytokine signalling by reducing the binding of IL-2 to IL-2Rα (EC50 ↑2.3-fold at pH 6.5)." (PMID 41429765, 2025). "As a model to study leukaemic tumour cells evasion from NK cells, we established a long-term in vitro co-culture system using IL-2-activated primary mouse NK cells co-incubated with NK cell–naïve DNA barcoded B-ALL cell lines for up to 20 days." (PMID 39642167, 2025). "IL-2-functionalized nanoparticles promote T-cell expansion and survival, thereby extending their anti-tumor activity." (PMID 40860882, 2025). "Optimizing IL-2 delivery methods to enhance its anti-tumor effects while minimizing side effects through adjustments in dosage and delivery strategies will likely be the focus of future studies." (PMID 41376630, 2025). "Fusion with monoclonal antibodies (e.g., antibodies against tumor-associated antigens, such as HER2 and CD22) or other targeting ligands (e.g., IL-2) creates ITs capable of specifically targeting specific tumor cells." (PMID 40303490, 2025). "Cytokines such as TNF-α, IL-1β, IL-2, and IL-6 can enhance tumor growth, angiogenesis, metastasis, and invasion by promoting the survival and proliferation of tumor cells through activation of the NF-κB pathway." (PMID 40172365, 2025). "Sorted CD8+ T cells were expanded with IL-2 or IL-7 and cocultured with tumor only (U87vIII); tumor + BRiTE; or phorbol myristate acetate (PMA)/ionomycin." (PMID 40244705, 2025). "Interleukin-2 (IL-2) stimulated the proliferation and activation of tumor infiltrating NK and T-cells." (PMID 40145650, 2025). "IL-2, in cooperation with cytokines such as IL-15, plays a pivotal role in enhancing the anti-tumor functions of natural killer (NK) cells." (PMID 40869161, 2025). "CD4+ T cells, particularly regulatory T cells (Tregs), can suppress CD8+ T-cell proliferation and cytotoxicity through inhibitory cytokines, IL-2 competition, and direct cell–cell contact, contributing to an immunosuppressive tumor microenvironment." (PMID 41008548, 2025). "CTLs, cytotoxic T‐cells lymphocytes; DCs, dendritic cells; ECM, extra cellular matrix; IFN‐γ, interferon‐γ; IL‐2, interleukin‐2; NK, natural killer cells; ROS, reactive oxygen species; TAMS, tumour associated macrophages, cells; Th‐1, T‐helper cell." (PMID 39308084, 2025). "Another approach would be to isolate NK cells from the patient’s peripheral blood, followed by in vitro stimulation with IL-2 and/or co-culture with K562 tumor cells, resulting in proliferation and activation." (PMID 40427186, 2025). "Several studies have observed the activation of CD8+ and CD4+ T cells when exposed to DCs exosomes associated with the induction of an anti-tumor immune response in vivo through exosomal CD80 and endogenous IL-2." (PMID 40141358, 2025). "The study administers CIML NK cells in combination with IL-2 to potentiate immune activation and enhance tumor cytotoxicity." (PMID 40498022, 2025). "CAR T-cells expressing o9R and receiving orthogonal IL-2 also exhibited greater anti-tumor activity in syngeneic mouse models compared to CAR T-cells expressing the orthogonal IL-2 receptor." (PMID 41019052, 2025). "The infused NK cells were supported by rh-IL2 (intraperitoneal injection), and tumor growth was monitored weekly via BLI." (PMID 41436559, 2025). "IFN-α exerts anti-tumor and immunomodulatory effects, while IL-2 promotes the proliferation and activation of T cells and NK cells." (PMID 41030448, 2025). "Combination therapy with IL-2 and PD-1 inhibitors improves T cell activation and tumor vascular normalization." (PMID 40177538, 2025). "IL-2 plays a key role in activating NK and T cells, essential for tumor immune surveillance and cytotoxicity." (PMID 40868199, 2025).
tumor (continued). "Numerous studies have demonstrated the involvement of HD IL-2 therapy in the stimulation of anti-tumor immune cells, which are able to counteract tumor progression." (PMID 41150778, 2025). "Collectively, pseudohypoxia induced by HIF-PH inhibitors enhances the tumor immune response via IL-2 induction by CD4+ T cells in the spleen and TME." (PMID 40343532, 2025). "This inhibition promotes T cell-mediated anti-tumor immune responses by upregulating costimulatory signals such as OX-40L and 4-1BBL, facilitating the release of IL-2, and reducing the expression of immune checkpoints." (PMID 40006729, 2025). "NaHCO3 raised the extracellular pH (pHe) in tumor tissues in vivo, which was followed by an increase in T cell infiltration, T cell activation, and upregulation of anti-tumor cytokines like IFN-γ, IL2, and IL12p40 in the tumor tissues." (PMID 40124335, 2025). "When the semi-quantitative IRS values were compared between tumour tissues and the corresponding margins, TNF-α, IFN-γ, IL-12 and IL-2 showed relatively lower expression in tumours, whereas IL-1β and IL-6 were elevated in tumour tissue." (PMID 41465261, 2025). "Tumor cells exploit the IL-2 signaling pathway to promote their proliferation and survival or alter the function of immune cells to evade immune surveillance." (PMID 39958351, 2025). "Inhibition of PGE2 signalling to EP2 and EP4 during TIL expansion for ACT resulted in increased IL-2 sensing, leading to enhanced proliferation of tumour-reactive TILs and enhanced tumour control once the cells were transferred in vivo." (PMID 38658764, 2024). "Treg cells were reduced in both spleen and tumor in the combination treatment group compared to the IL-2 treatment group or the P-IL-2 treatment group." (PMID 38352877, 2024). "In IPCGOR and IL-2 therapy, IL-2 acts as a potent immune stimulant, promoting the proliferation and activation of NK cells and CTLs, key to targeting and destroying tumor cells 32-33." (PMID 38434976, 2024). "IL-2 is also being tested for clinical use in other tumor settings, mainly in combination with other forms of treatment." (PMID 38545115, 2024). "Cytokines, including TNF-a, IFN-g, and IL-2, have been demonstrated to have anti-tumor effects in vitro." (PMID 39011219, 2024). "This strain was programmed to secrete mouse-activated Interleukin-2 (IL-2) to stimulate T cell proliferation for tumor immunotherapy." (PMID 39286511, 2024). "In a retrospective analysis, HD IL-2 showed durable anti-tumor activity in patients after progression following PD-1 pathway blockade, with a toxicity profile expected from HD IL-2." (PMID 39114660, 2024). "TIL therapy involves isolating these cells from the tumour, cultivating them in vitro, and reinfusing them into the patient with a high dose of IL-2 after lymphodepletion to enhance T cell survival and target tumour cells." (PMID 39450176, 2024). "Cytokines released by T cells, such as IL-2 and IL-15, have been shown to activate NK cell cytotoxicity and enhance anti-tumor responses." (PMID 39221244, 2024). "The BIND combined with t‐CNV, mRNA vaccine, IL‐2, and anti‐PD‐1 antibody also significantly enhanced cancer immunotherapy by the dynamic modulation of immunological landscape of tumor microenvironment." (PMID 39380383, 2024). "A. muciniphila and IL-2 treated mice demonstrated statistically significant tumor volume and survival rate." (PMID 38585738, 2024). "In a preclinical study, an adenovirus encoding tumor necrosis factor-α and interleukin-2 was found that induce the formation of TLS, enhance ICB efficacy, inhibit tumor growth, and prolong survival in head and neck tumor-bearing mice." (PMID 38583352, 2024). "It has been shown to reduce the secretion of IFN-γ, TNF-α, and IL-2, which are essential for effective anti-tumor responses." (PMID 39766353, 2024).
tumor (continued). "Our results firstly discovered that PTT increased anti-tumor immunity on the basis of effectively suppressing Gal-9 in splenic DCs, reducing T cell apoptosis, inducing IL-2 release in spleen, enhancing tumor-Ag-specific T cell response." (PMID 38366083, 2024). "Validating DSP counts with multiplex immunofluorescence, they then identified an Interleukin-2 (IL2) axis between tumor and stroma compartments, and hence IL2 receptor alpha (CD25) as a potential predictive biomarker of response." (PMID 38064127, 2024). "Signaling through the B cell antigen receptor is vital for B cell maturation and function, and changes in the IL2 pathway and PD-1 signaling are related to tumor immune regulatory mechanisms." (PMID 38922500, 2024). "We conducted tumor treatment-related immune cell and Th1/Th2 subset detection in the patient, comparing the concentrations of 6 cytokines (IL-2, IL-4, IL-6, IL-10, TNF-α, and TNF-γ) and various immune cells in peripheral blood before and after treatment." (PMID 39871939, 2024). "Typically, multiple fragments from a single tumor are cultured independently in wells containing high‐dose IL‐2." (PMID 39422665, 2024). "While IL-2 alone or activated NK cells alone showed little tumor regression, the combined treatment resulted in marked regression in several patients, leading to its approval by the FDA." (PMID 38545115, 2024). "After expansion with IL-2, we tested the tumor killing activity of the expanded OT-I CD8 cells against B16-OVA cells in vitro." (PMID 38789421, 2024). "Mice treated with 2aG4–IL-2 had a longer survival rate compared to the non-tumor targeted IL-2 control group in the context of vaccination." (PMID 39204319, 2024). "High-throughput genetic screening of T cells is conducted through TCR stimulation with anti-CD3/CD28 and IL-2, co-culturing with tumor cells (in vitro), or implantation in tumor-bearing mice (in vivo)." (PMID 39538305, 2024). "NK Cell Expansion and Activation: Expanding the CAR-NK cells using cytokines (IL-2, 15, 18, 21, and 12) and activating them for optimal anti-tumor activity." (PMID 39763648, 2024). "Multiple studies have demonstrated the safe delivery of IL-2 to the tumor microenvironment using oncolytic adenoviruses." (PMID 38910324, 2024). "In anti-tumor therapy with high-dose IL-2, activation of effector T cells is accompanied by activation of regulatory T cells, leading to immune activation." (PMID 38352877, 2024). "TIL therapy involves isolating this population of cells from the tumor, using IL‐2 stimulation and thus expanding them in an in vitro laboratory setting, and finally re‐injecting them into the patient." (PMID 39286776, 2024). "This formulation effectively prolonged the half-life of IL-2, and its ROS responsiveness facilitated drug release at the tumor site." (PMID 38352877, 2024). "Tumor Treg depletion by IL‐2‐Fc was most evident in our early time point monotherapy studies, especially 1 day posttreatment in our MC38/CEA short term study, with some mice reaching a >50‐fold higher IFNγ+CD8+/Treg ratio." (PMID 38317590, 2024). "Activated T cells produce IL-2 associated with T cell proliferation and IFN-γ which activates tumor-suppressive macrophages." (PMID 38201640, 2024). "Recombinant L19 monoclonal antibody bound to IL-2 (L19IL2) allows for targeted delivery of IL-2 to the site of the tumor, reducing systemic toxicities." (PMID 39682188, 2024). "Adoptive immunotherapy using NK cells in combination with cytokines including IL-2 (it mediates NK cell activation and proliferation) is an important treatment for patients with different tumours or leukemia." (PMID 38475858, 2024). "While these therapies differ in their approach to generating tumor-responsive T cells, each has historically relied upon extensive ex vivo expansion of T cells, most commonly with IL-2." (PMID 38789421, 2024).
tumor (continued). "This blockade leads to an increased production of interleukin 2 (IL-2) and creates an environment conducive to immune-mediated tumor destruction." (PMID 39229331, 2024). "MDSCs in tumours release arginase, depriving T cells of crucial amino acids and lowering IL-2 and IFN-γ levels." (PMID 39596267, 2024). "This will, in turn, inhibit the production of anti-tumor cytokines, such as IL-2 and IFN-γ, leading to a decrease in effector cells necessary to control tumor growth." (PMID 39061427, 2024). "Hubbell team developed the CBD-fused IL-2 (CBD-IL-2) that exhibits tumor localization after intravenous administration." (PMID 39664443, 2024). "Tumor cell-derived MIF promotes expansion of Tregs (consistent with the IL-2 ARP we observed in CD4+ T cells via ASPEN) and inhibits CD8+ T cell activation." (PMID 39483921, 2024). "An adenovirus encoding B7-1 (Ad.mB7-1) and B7-2 (Ad.mB7-2), ligands for T cell receptor CD28, were coupled with adenoviral-IL-2 delivery in PyMT and neu tumors to induce complete tumor regression after a single i.t. injection in a mouse model." (PMID 38803496, 2024). "First, we observed that B7-H3-CXCR2 CAR T cells produced significantly more cytokines (IFNγ and IL-2) following tumor cell target engagement." (PMID 38554158, 2024). "In comparison to PD-1+LAG-3- cells, PD-1+LAG-3+ T cells within the tumor exhibited a diminished ability to generate cytokines, including IL-2 and IFN-γ, as well as granules such as perforin (PFN) and granzyme B (GzmB)." (PMID 38390331, 2024). "Since we previously showed that SRT plus targeted ICK elicited immune memory in the MC38/CEA model, we combined SRT plus ICK or IL‐2‐Fc therapy to determine the added effect of tumor targeting in the same subcutaneous MC38/CEA mouse model." (PMID 38317590, 2024). "In neu tumors, 13/20 completely regressed in Ad.mB7-1/hIL-2, 9/15 in mB7-2/IL-2, demonstrating tumor dependent differences in response." (PMID 38803496, 2024). "The ELISA test showed the levels of IFN-γ and IL-2 increased in cancer nodules, indicating that anti-tumor immunity had been activated." (PMID 38589867, 2024). "Th1 cells primarily secrete cytokines such as TNF-α, IFN-γ and IL-2, playing a crucial role in anti-tumor immunity." (PMID 38792234, 2024). "In a recent publication it was shown that the acidic pH in the tumor interferes with the binding of native IL-2 to CD25, resulting in reduced STAT5 phosphorylation, effector differentiation, and antitumor immunity by CD8+ T cells." (PMID 39114660, 2024). "Compared to DCs obtained through the traditional method (cultured in medium containing GM-CSF and IL-4), DCs cultured with PBMCs, and IL-2 exhibited increased tumor infiltration capacity, potentially facilitating sustained T cell immunity." (PMID 38554155, 2024). "High lactate secretion is one of the main characteristics of tumor cells; therefore, we evaluated the effect of IL-2 on lactate secretion." (PMID 38999946, 2024). "CD4 + T cells can directly secrete cytokines such as IFN-α, TNF-γ, IL-2, which have anti-tumor effects, and also activate immune effector cells such as CD8 + T cells and NK cells to indirectly exert anti-tumor effects." (PMID 38834662, 2024). "Secondly, T-lymphocytes secrete cytokines such as interferon-γ (IFN-γ) and interleukin-2 (IL-2), which enhance the immune system’s ability to surveil and attack tumor cells." (PMID 38344202, 2024). "Natural killer cells treated with statins and IL-2 have shown increased production of cytokines with cytotoxic effects on tumour cells." (PMID 39042634, 2024). "The transferred CTLs pretreated with UA substantially enhanced the IFN‐γ, TNF‐α, IL‐2, and granzyme B‐producing capacity in the tumor, spleen, and lymph node." (PMID 38447147, 2024).
tumor (continued). "We developed a strategy to enhance the anti-tumor efficacy of IL-2 therapy by selectively enhancing the expansion and activation of CD8+ T cells over Tregs in tumors with abundant PD-L1 expression." (PMID 38834889, 2024). "The authors concluded that electrochemotherapy plus IL-2 gene electrotransfer and IL-2 systemic administration improved patient outcomes by decreasing in vivo tumor growth." (PMID 39728976, 2024). "The TME contains chemicals such tumor antigens, IL-2, IL-10, TGF-β, and other soluble molecules that stimulate the T-cell receptor (TCR) and enhance the transformation of naive CD4+ T-cells into iTregs." (PMID 38509593, 2024). "The authors identified that the combination of sBTLA and an HSP70 vaccine significantly improved the anti-tumor immune response, with combination treatment increasing expression of IL-2, IFN-γ, and CD8+ TILs, and reducing expression of IL-10, TGF-β, and Foxp3." (PMID 38822401, 2024). "The results demonstrated that lymphocytes cultured with oncogenes-transfected tumor cells promoted an increase in the release of the cytokines IL-2, IL-4, IL-10, and TNF-α, with differences in the releases from different transfected oncoproteins." (PMID 39599846, 2024). "Such a reduction indicates that the inhibitory effect of Palbociclib on Treg cells antagonized the activating effect of IL-2 on Treg cells, thus further enhancing the tumor effect by improving the immune microenvironment." (PMID 38352877, 2024). "Elimination of non-tumor B cells was analyzed by performing a flow cytometry-based cytotoxicity assay and T cell-mediated release of the pro-inflammatory cytokines IL-2 and IFN-γ was determined using ELISA." (PMID 38340727, 2024). "Significant inhibition of tumor growth was observed, along with differences in the levels of measured cytokines such as IL-2, TNF-α, IFN-γ, and IL-4." (PMID 39367471, 2024). "For instance, cytokines such as interleukin-2 (IL-2) can increase the effectiveness of NK cells and CTLs against tumor cells by amplifying and activating their functions." (PMID 39199299, 2024). "This shift will increase the immunosuppressive cytokines (IL-2, IL-4, IL-7, IL-13, and IL-15) production by neoplastic elements which lead to tumor growth and spread." (PMID 38850434, 2024). "Compared to the model group, Sor treatment significantly reduced IL-2 levels in the peripheral blood of tumor-bearing mice (P < 0.05)." (PMID 38312647, 2024). "Interleukin 2 is a cytokine involved in activation of T regulatory cells, playing a role in central tolerance and tumor immunity." (PMID 38773194, 2024). "In a study designed to test the effects of reovirus on DCs, NK cells co-cultured with DCs exposed to reovirus (reo-DCs) displayed enhanced tumor-killing efficacy compared to NK cells treated with IL-2 or NK cells co-cultured with untreated DCs." (PMID 39066359, 2024). "Given that exhausted T cells showed impaired cytokine production, we investigated the expression levels of TNF-α, IFN-γ and IL-2 in tumor-infiltrating T cells." (PMID 38287103, 2024). "The anti-tumor properties of IL-2 and IL-15 have been reported, and IL-15 has been highlighted as a potential biomarker and therapeutic target in CRC." (PMID 39456247, 2024). "Integrating these findings with the flow cytometry analysis of CD8+ T cells and Treg cells within the tumor locale, it is deduced that the combination treatment group effectively reversed the tumor microenvironment compared to the IL-2 alone treatment group." (PMID 38352877, 2024). "Lymphokine-activated killer (LAK) cells, primarily derived from NK cells and T-lymphocytes, are activated by interleukin-2 (IL-2) and exhibit potent cytotoxic activity against tumor cells." (PMID 39468695, 2024). "Mechanistically, TET2 mediated IL-2/STAT5A signaling epigenetically upregulates tumor cGAS expression and produces cGAMP." (PMID 38177099, 2024).